ACE (angiotensin I converting enzyme)
Diseases named in the same sentence as ACE in open-access papers (continued):
Sharing a sentence is not in itself a finding about the gene and the disease.
heart failure (continued). "Currently, the inhibition of the renin–angiotensin system (RAS) using angiotensin-converting enzyme (ACE) inhibitors and angiotensin receptor blockers (ARBs) is the most validated clinical strategy for treating patients with advanced heart failure." (PMID 29259712, 2017). "Suppression of the renin–angiotensin system (RAS) by angiotensin-converting enzyme (ACE)-inhibitors remains the mainstay of treatment for heart failure." (PMID 26871774, 2016). "Increasing body of evidence indicates the presence of ACE and supports its role in the intracellular production of Ang II in cardiomyocytes, heart failure and myocardial infarction." (PMID 27814397, 2016). "A review concluded that the median prevalence of use of ACE inhibitors in patients with heart failure and reduced ejection fraction was found to be 71% in patients discharged from hospitals and 86% in patients discharged from specialty clinics." (PMID 27630801, 2016). "In the treatment of heart failure, both ACE inhibitors and ARBs have been demonstrated to maintain the normal expression of LZ+ MYPT1 expression and sensitivity to NO-mediated vasodilatation." (PMID 27037223, 2016). "Currently, beta-blockers and angiotensin converting enzyme (ACE) inhibitors or angiotensin receptor blockers (ARBs) are the first line of treatment in heart failure patients." (PMID 27667975, 2016). "A wealth of evidence has demonstrated that inhibition of a hyperactive SNA by ACE inhibitors, ARBs or β-blockers protects against LV remodeling and heart failure." (PMID 27391436, 2016). "Inhibition of the renin–angiotensin system (RAS) via angiotensin-converting enzyme (ACE)-inhibitors is the main treatment for heart failure." (PMID 26871774, 2016). "For example, one of the first experimental observations was that ACE increased in heart failure, its cardiac induction was tissue specific, and it correlated with the size of myocardial infarction." (PMID 27652272, 2016). "Heart failure therapies were used as follows: β-adrenoceptor antagonists in 81%, ACE inhibitors or angiotensin receptor blockers in 89%, mineralocorticoid receptor antagonists in 41%, cardiac resynchronisation therapy in 29% and ICD in 13%." (PMID 26857212, 2016). "A paradigm shift in RAAS understanding occurred when the CONSENSUS and the SOLVD trials showed that the ACE inhibitor Enalapril reduced overall mortality by 27% and 16% in patients with heart failure." (PMID 27652272, 2016). "Among the START criteria the most frequently identified PPO were ACE inhibitors in patients with heart failure (12.8%) and oral anticoagulation in the presence of chronic atrial fibrillation (12.8%)." (PMID 25887546, 2015). "Most patients will improve with a standard heart failure regimen that includes ACE inhibitors or ARBs, beta blockers, and diuretics." (PMID 26413355, 2015). "Most BP lowering drugs such as diuretics, beta-blockers, ACE inhibitors, and angiotensin receptor blockers are effective in the prevention of heart failure." (PMID 26893917, 2015). "Several studies have reported the efficacy of ACE inhibitors in preventing AF and a meta-analysis found that the greatest reduction in AF was in patients with heart failure." (PMID 28392870, 2014). "The observation that ACE mRNA content was increased 3 days after MI corroborates the results of several previous studies of experimental MI and of humans with MI and cardiac failure." (PMID 24991808, 2014). "A large number of clinical and experimental studies provide the solid evidence that ACE plays a central role in the pathogenesis of cardiac hypertrophy and fibrosis and heart failure." (PMID 25471116, 2014). "ACE inhibitors are often used to treat heart failure in CS, and serum ACE levels are therefore likely to be influenced by this treatment." (PMID 25250336, 2014). "Of note, a high proportion of participants were treated with evidence-based heart failure therapy, including 90.3% who were on beta-blockers and 98.5% who were on ACE-inhibitors or ARBs." (PMID 25426862, 2014).
heart failure (continued). "Most participants were on evidence-based heart failure therapies on admission including angiotensin-converting enzyme (ACE) inhibitors (53%, 8/15) and beta-blockers (86%, 13/15)." (PMID 23478028, 2013). "Clinical studies seem to suggest that the pharmacological benefits of ACE inhibition and β-adrenergic receptor blockade, in human heart failure, are at least partly attributable to interruption of apoptosis." (PMID 23441146, 2013). "These are significant findings as ACE inhibitors now form the cornerstone of the management plan for heart failure." (PMID 24454410, 2013). "Even the combination of ACE inhibition and angiotensin II antagonism only transiently reduces aldosterone plasma levels in patients with heart failure suggesting angiotensin II independent aldosterone production." (PMID 23909633, 2013). "Overall, there are high rates of heart failure medication usage at the time of enrollment with 90% of individuals taking β‐blockers and 88% taking angiotensin‐converting enzyme inhibitors (ACE‐Is) or angiotensin receptor blockers." (PMID 23525420, 2013). "29.5% of DMD and 23.8% of BMD registrants were prescribed one cardiac medicine at least, and ACE–inhibitor was the most common medicine for cardiac failure." (PMID 23601510, 2013). "Treatment with ACE inhibitors after MI has been found to attenuate pathologic left ventricle remodeling, the incidence of heart failure, and mortality." (PMID 22333273, 2012). "Our findings regarding CHD medication are in line with previous research: The results of the Euro Heart Survey on Heart Failure including 8,914 patients with heart failure showed that women got less ACE inhibitors and beta-blockers than men." (PMID 22838970, 2012). "A German cross-sectional study on 1,857 consecutive patients with heart failure likewise showed a difference in the prescription of ACE inhibitors and dosage of beta-blockers, and revealed a less evidence-based treatment in women than in men." (PMID 22838970, 2012). "Angiotensin converting enzyme (ACE)-inhibitors came out inferior to calcium-channel blockers (CCB) regarding stroke-risk (RR 1.19; 1.03 to 1.38), but superior regarding risk of heart failure (RR 0.82; 0.69 to 0.94), both based on moderate quality evidence." (PMID 22480336, 2012). "The Carvedilol and ACE-inhibitor Remodeling Mild Heart Failure Evaluation (CARMEN) trial randomized participants with mild heart failure to: enalapril, carvedilol, or both." (PMID 22928146, 2012). "Most patients in this study were treated with both statins as well as ACE inhibitors or AT II antagonists known to improve endothelial function in patients with heart failure." (PMID 21999413, 2011). "After initiation of conventional heart failure therapy with ACE-inhibitors, diuretics and low dose beta-blockers the patient was easily weaned off the IABP and discharged home four weeks after admission." (PMID 21392383, 2011). "For example, compared with cardiologists, family practitioners and general internists probably underutilize ACE inhibitors due to less knowledge about heart failure and poor adherence to guidelines." (PMID 21609462, 2011). "Early treatment by ACE inhibitors after myocardial infarction (MI) decreases adverse remodeling of the left ventricle, the incidence of heart failure, and mortality." (PMID 21162760, 2010). "Several trials and studies proved a positive influence of treatment by ACE inhibitors for the progression of LV remodeling and heart failure." (PMID 21162760, 2010). "There is a clear-cut and compelling evidence that all patients with heart failure and asymptomatic left ventricular dysfunction should receive ACE inhibitor therapy." (PMID 21150007, 2010). "Two well conducted meta-analyses of ACE-inhibitors in more than 19,000 patients yielded similar reductions in heart failure mortality between men (OR 0.76, 95% CI 0.65–0.88) and women (OR 0.79, 95% CI 0.59–1.06) compared with placebo." (PMID 20689584, 2010).
heart failure (continued). "Unexpectedly and perhaps inexplicably, the ACE inhibitor had higher rates of combined cardiovascular disease, stroke and heart failure." (PMID 19287817, 2009). "For advanced heart failure patients, angiotensin-converting enzyme (ACE) inhibitors were the first medication to achieve a reduction in mortality of 40% at six months." (PMID 19466294, 2009). "Severe heart failure in children is commonly treated with diuretics, ACE inhibitors, calcium blockers, β-blockers and vasodilators." (PMID 19775464, 2009). "With regard to combination treatments, patients with heart failure were more likely to be prescribed an ACE inhibitor plus a diuretic (60% versus 31.3% for all patients), as were patients with renal insufficiency (40.7%)." (PMID 20003298, 2009). "Clinical heart failure and treatment with ACE-inhibitors were more common among those with highest peak CRP concentration, probably reflecting more extensive myocardial infarction." (PMID 19583836, 2009). "Patients with heart failure were more likely to be prescribed ACE inhibitors (32.8% versus 24.5% for all patients) and diuretics (23.4% versus 15.7%), and less likely to be prescribed beta-blockers (12.5% versus 29.4%)." (PMID 20003298, 2009). "The data showed that in these patients with heart failure, the addition of spironolactone to an ACE inhibitor, or the use of losartan on its own, or the combination of losartan plus spironolactone induced a favourable sympathovagal balance." (PMID 19104723, 2008). "In a subgroup analysis, ACE inhibitors have been proved a beneficial effect only for the patients with bundle branch blocks, heart failure or diabetes mellitus." (PMID 20108509, 2008). "In these patients, ACE inhibitors limit the expansion of the infarction, lower reinfarction rate, lower the incidence of new onset heart failure and represent the state-of-the-art therapy for them." (PMID 20108509, 2008). "Precautions for angiotensin II receptor blocker use in patients with renovascular hypertension, hypovolemia, and severe heart failure are the same as those for ACE inhibitors." (PMID 18947424, 2008). "The data derived here indicate that in patients with heart failure, the addition of spironolactone to an ACE inhibitor, the use of losartan on its own, or the combination of losartan plus spironolactone all induced a favourable sympathovagal balance." (PMID 19104723, 2008). "• The options for a patient with severe heart failure who has responded well to an ACE inhibitor, but has persistent cough: stop the medication altogether, try a lower dose, or change to an angiotensin receptor blocker?" (PMID 17615054, 2007). "The 10 patients in functional class III/IV who survived received complete medical treatment for heart failure (digitalis, ACE inhibitors, diuretic, beta blockers and antiplatelet agents and/or anticoagulants)." (PMID 17002802, 2006). "The first-line calcium channel blocker caused more heart failure compared to the THZ and ACE inhibitor." (PMID 15839739, 2005). "An earlier study on the role of ACE inhibitors in patients with heart failure and AF showed a trend towards more patients maintaining sinus rhythm after ECV when instituted on lisinopril in comparison to patients not treated with lisinopril." (PMID 15667649, 2005). "A previous model-independent analysis in ACE inhibitor-naïve children with heart failure from the LENA project showed a significant increase in plasma renin activity at the dose confirmation visit, which took place on average 5 days after the first dose of enalapril." (PMID 41155980, 2025). "Clinical trials have underscored thetherapeutic importance of ACE inhibitors in heart failure." (PMID 41209135, 2025). "In addition, supportive treatments for heart failure, including diuretics, ACE inhibitors, and beta-blockers, are employed, although caution is needed due to the potential for hypotension and bradycardia." (PMID 41295360, 2025).
heart failure (continued). "However, there was a high disparity in the use of heart failure medications (e.g. in interstage I-II 35% use ACE-inhibitors, and only 26% digoxin)." (PMID 40448872, 2025). "Consequently, it can be assumed that the angiotensin II/angiotensin I ratio can also serve as a measure of in vivo ACE activity in children with heart failure." (PMID 41155980, 2025). "Furthermore, evidence from animal studies is supported by observations from human studies, which reported beneficial effects of AT1R blockers and angiotensin-converting enzyme (ACE) inhibitors in treating diabetic patients with heart failure." (PMID 40149735, 2025). "Another explanation could be that more unbound enalaprilat is available for ACE inhibition in children with heart failure than in healthy adults." (PMID 41155980, 2025). "The prevalence of heart failure is continuously growing despite the implementation of the four pillars of heart failure treatment: angiotensin-converting enzyme inhibitors (ACE inhibitors) or angiotensin II receptor blockers (ARBs), beta-blockers, aldosterone antagonists, and SGLT-II inhibitors." (PMID 40431475, 2025). "Management may include supportive therapies such as β-blockers, ACE inhibitors, or mineralocorticoid receptor antagonists, which are commonly used in heart failure treatment." (PMID 40880646, 2025). "The study had to assess the effectiveness of SGLT2i in comparison with usual care that implements heart failure guidelines with dietary intervention and pharmacotherapy, including beta-blockers, ACE inhibitors, ARBs, and mineralocorticoid receptor antagonists (MRA)." (PMID 41527634, 2025). "Thus, the inhibition of ACE can help to regulate the blood pressure in hypertensive persons and the treatment of various cardiovascular diseases such as heart failure, myocardial infarction, diabetic nephropathy, or renal dysfunction." (PMID 40292100, 2025). "Since the change in the angiotensin II/angiotensin I ratio results from ACE inhibition, a different binding affinity of enalaprilat to ACE in children with heart failure could be a possible reason." (PMID 41155980, 2025). "In addition, a population pharmacodynamic model was developed based on simultaneous pharmacokinetic and pharmacodynamic measurements in ACE inhibitor-naïve children with heart failure from the LENA project." (PMID 41155980, 2025). "The management of cirrhotic cardiomyopathy is generally similar to that of heart failure, including angiotensin-converting enzyme (ACE) inhibitors, angiotensin receptor blockers (ARBs), loop and thiazide diuretics, aldosterone receptor antagonists, and beta-blockers." (PMID 39982238, 2025). "Additionally, in a pressure-induced model of heart failure, sGC stimulators mitigated cardiac fibrosis by inhibiting the expression and activity of angiotensin-converting enzyme (ACE), thereby reducing angiotensin II production in the myocardium." (PMID 40940810, 2025). "Several heart failure medications, including beta‐blockers, ACE inhibitors, and diuretics, may be excreted in breast milk and could potentially cause adverse effects in infants—such as bradycardia, hypotension, fluid loss, and electrolyte imbalances." (PMID 41031274, 2025). "Angiotensin receptor blockers, angiotensin-converting enzyme (ACE) inhibitors, angiotensin receptor–neprilysin inhibitors, and sodium-glucose cotransporter 2 inhibitors have been shown to reduce the progression of heart failure, ameliorate symptoms, and prevent its complications." (PMID 40608209, 2025). "These strategies include antiarrhythmic drugs for atrial and ventricular arrhythmias, implantation of pacemaker and ICD devices for conduction abnormalities and sudden cardiac death prevention, and regular heart failure treatments including beta blockers, ACE inhibitors, and ARNIs." (PMID 41303475, 2025). "In some cases, treatment of heart failure may include the use of drugs such as ACE inhibitors, beta-blockers, and diuretics to help improve cardiac function." (PMID 41375786, 2025).
heart failure (continued). "Common treatments for heart failure include ACE inhibitors, beta-blockers, and mineralocorticoids." (PMID 40729215, 2024). "Before enrolment, 49 (45%) participants were on a cardiac medication due to clinical signs and symptoms of heart failure in the peripartum time period (42 participants on furosemide, 14 on ACE-inhibitor, 10 on a beta-blocking agent, 4 on spironolactone, 4 on digoxin, and 5 on bromocriptine)." (PMID 38724901, 2024). "However, among patients with severe heart failure, ARBs demonstrated a higher incremental cost-effectiveness ratio compared with ACE inhibitors, suggesting reduced cost-effectiveness in this subgroup." (PMID 39252272, 2024). "A meta-analysis published in 2000 that included three large trials (SAVE, TRACE, AIRE) concluded that ACE inhibitors administered 48 h from the onset of AMI caused a decrease in mortality, a reduction in the risk of heart failure and the number of hospitalizations for this condition." (PMID 39062156, 2024). "For arrhythmias and heart failure, guideline-directed therapies recommend heart failure drugs such as angiotensin-converting enzyme inhibitors (ACE-Is), angiotensin receptor blockers (ARBs), beta-blockers, sodium-glucose cotransporter 2 inhibitors, and mineralocorticoid receptor antagonists." (PMID 38681683, 2024). "Given that a large number of the included studies focus on patients with heart failure, it is important to remember that medications like diuretics, angiotensin-converting enzyme (ACE), and vasodilators, which are commonly prescribed for cardiovascular conditions, can affect lipid levels." (PMID 38755142, 2024). "Examples include beta-blockers prescribed for atrial fibrillation, diuretics in patients with symptomatic heart failure, and ACE inhibitors/angiotensin II receptor blockers/aldosterone antagonists or beta-blockers in patients with heart failure and reduced left ventricular ejection fraction." (PMID 38305846, 2024). "Traditional heart failure therapies, including ACE inhibitors, β-blockers, and diuretics, primarily control symptoms by reducing cardiac workload and improving cardiac pumping function; however, they are often accompanied by adverse reactions, such as hypotension and impaired kidney function." (PMID 39600362, 2024). "In addition, therapy of heart failure in the form of ACE inhibitors (perindopril), loop diuretics (torasemide), mineralocorticoid receptor antagonists (eplerenone) was constantly performed." (PMID 39337571, 2024). "Ensure guideline-directed medical therapy for heart failure is instituted, particularly that patients are on angiotensin-converting enzyme (ACE) inhibitors, angiotensin II receptor blockers, or angiotensin receptor neprilysin inhibitor if no contraindication given possible cognitive protection." (PMID 38068464, 2023). "Conversely, medications that antagonize the effect of ACE inhibitors/ARBs or diuretics (e.g., NSAIDs) might contribute to heart failure exacerbations." (PMID 36817138, 2023). "However, rates of heart failure’s long term pharmacological treatments (beta blockers, ACE and ARN inhibitors, MRA) were equally distributed between groups." (PMID 36776263, 2023). "This drug was evaluated in a double-blind, randomized, multinational trial, the Prospective Comparison of Angiotensin Receptor Neprilysin Inhibitors with ACE Inhibitors to Determine Impact on Global Mortality and Morbidity in Heart Failure trial (PARADIGM-HF trial)." (PMID 37181979, 2023). "The main drugs used to treat heart failure are diuretics, angiotensin-converting enzyme (ACE) inhibitors, angiotensin receptor blockers (ARBs), β-blockers, and salt corticosteroid receptor antagonists (MRAs), but the morbidity and mortality rates of the disease remain high." (PMID 37426419, 2023).